IL7R (interleukin 7 receptor)
Diseases named in the same sentence as IL7R in open-access papers (continued):
Sharing a sentence is not in itself a finding about the gene and the disease.
tumor (continued). "However, while T cells can be readily detected in the spleens of Il7r−/− tumour-bearing mice, we detected very few T cells in the tumours of Il7r−/− mice, suggesting a role for IL-7R signalling in T-cell trafficking into tumour and/or survival of T cells in tumour." (PMID 27498556, 2016). "As a result, a strong positive correlation (Pearson, r=0,787 was seen between Zeb2 and Il7r mRNA expression levels in our mouse and human (Pearson, r=0.735) immature/ETP-ALL tumours." (PMID 25565005, 2015). "At day 101, 8 days after tumor challenge, the OVA257–264-specific CD8+ T cell population down-regulated IL-7Rα and CD62L indicating a return to a predominant effector phenotype." (PMID 22359671, 2012). "In C1-GBM, key tumor driver genes included BIRC3 (Baculoviral IAP Repeat Containing 3), MET (MET Proto-Oncogene, Receptor Tyrosine Kinase), COL1A1 (Collagen Type I Alpha 1 Chain), CR1 (Complement C3b/C4b Receptor 1), and IL7R (Interleukin 7 Receptor)." (PMID 41614933, 2026). "The expression levels of IL7R, IRF8, and PTPRC were significantly upregulated in recurrent tumors, compared with primary tumors, and correlated strongly with one another across both tumor types (p < 0.05)." (PMID 41596598, 2026). "Functional validation further demonstrated that IL7R, IRF8, and PTPRC contribute to tumor progression by promoting immune evasion, whereas NSG1 might have tumor-suppressive effects." (PMID 41596598, 2026). "It has been demonstrated that IL7R mutations activate downstream IL7R signaling independent of IL7 and promote cell transformation and tumor formation, indicating that IL7R exon 6 mutations are gain-of-function mutations." (PMID 41048344, 2025). "As IL7R expression by naive T cells is downregulated following T cell activation through the TCR/CD3 complex,48IL7R expression in the tumor at day 16 may reflect the number of recently recruited naive T cells." (PMID 40239619, 2025). "Activation of genes related to this pathway (CSF2, SERPINE1, PDGFD, CYFIP2, IL7R, MYB, CSF1) can promote tumor cell proliferation and survival, and may also affect immune cells in the TME." (PMID 41328768, 2025). "The recruitment of naive T cells to the tumor, suggested by increased expression at day 16 of IL7R, may increase the likelihood of epitope spread, by exposing T cells with a wider range of TCR specificities to tumor antigens." (PMID 40239619, 2025). "In the tumor of patient UC3, most of the cells were of the resident IL7R+ phenotype." (PMID 41312368, 2025). "This suggests that high IL7R expression is a potent predictor of PFS in late-stage patients who have undergone optimal debulking surgery, and clinical management should be stratified according to tumor stage." (PMID 41360767, 2025). "While CCL5, CD52, DSTN and IL7R still exhibited a trend of high expression in tumour samples, but no significant discrepancy existed." (PMID 39098994, 2024). "Within the tumor, Lrp10+/+ CD8 T cells showed >50% reduction in cell surface IL7R." (PMID 38956225, 2024). "We show that tumor cells have an increased expression of several markers (CD47, IL7R, NKG7, CD80, CD84, CSF1R, NLRC5/CITA, CD2 and IRF3) that may be involved in regulating the level of immune infiltration and the effect on tumor immunity." (PMID 39001353, 2024). "Furthermore, dex elevated IL-7Rα expression, enhancing responsiveness to IL-7 and consequently improved CAR T cells' anti-tumor activity." (PMID 38140726, 2024). "By supplementing IL-7 during the in vitro expansion of CAR-T cells, constructing CAR-T cells that express IL-7 or IL-7R, or treating mice with modified IL-7 following CAR-T infusion, the persistence and anti-tumor efficacy of CAR-T cells can be significantly enhanced." (PMID 39906740, 2024). "It recapitulated the key features detected by flow cytometry, including high expression of IL-7R, absence of exhaustion markers and tumor-specificity." (PMID 37459511, 2023).
tumor (continued). "Mice treated with IL-7R blocking antibody after priming, but not during rechallenge, failed to form functional antitumor memory and exhibited tumor formation and growth identical to naive mice upon rechallenge." (PMID 37459511, 2023). "The IL-7R level decreased, and that of CA19-9 increased, with increasing tumor size." (PMID 35159120, 2022). "This indicates that the OIP5-AS1-PTPRC/IL7R/CD69 and MALAT1-IL7R/CD69 axes in SKCM may affect the tumor immune microenvironment, leading to SKCM progression." (PMID 36032150, 2022). "Next, we employed lineage-specific markers to annotate clusters into major cell types of the tumor, including T cells (CD3G, CD4, CD8A, CD28, and IL7R), B cells (CD19 and CD20), myeloid cells (HLA-DRA and CD14), fibroblasts (THY1 and ACTA2), and tumor cells (EPCAM and S100A)." (PMID 35634306, 2022). "The expression levels of CD69, IL7R, and PTPRC decreased with the progression of tumor stages." (PMID 36032150, 2022). "Also, in recurrent cSCC, IL7R+ CAFs showed interactions with TSKs by expressing EMT-related markers, possibly promoting the EMT of tumor cells." (PMID 36438481, 2022). "Importantly, some of these experimentally validated bystander cells had a transcriptional phenotype similar to tumor-specific progenitor PD-1+ CD8+ T cells characterized in other studies, marked by expression of IL7R (CD127), TOX, and TCF7 (TCF-1)." (PMID 35584630, 2022). "The majority (>97.68%) of CD8_C6_IL7R, CD8_C7_GZMK, CD8_C8_MHC, CD8_C9_XCL, CD8_C10_MKI67, and CD8_C11_PDCD1 were found in NPC tumours, whereas the majority (>94.85%) of CD8_C1_LEF1, CD8_C2_TCF7, CD8_C3_KLRB1, CD8_C4_KLRG1, and CD8_C5_CX3CR1 were in the peripheral blood." (PMID 33531485, 2021). "Moreover, in the sequence of our kinase-directed functional screening, we demonstrated that SK pharmacological inhibitors abrogate IL-7R-mediated signaling, promote mutant IL7R ALL cell death, and delay tumor growth." (PMID 34907175, 2021). "The tumor tissues derived from basal, Her2, LumA, and LumB breast tissues were not significantly different between normal and tumor ones; for IL7R: the expression levels are displayed in the box plot." (PMID 34572798, 2021). "TRUCKs with constitutive IL7R signaling increased T-cell proliferation, survival, and tumor-killing activity upon exposure to tumor antigens, without stimulating bystander lymphocytes in murine cancer models." (PMID 33381115, 2020). "From our results, we found that hypomethylation in IL7R led to a high expression in OSCC samples, which may affect the anti-tumor immune response during tumorigenesis." (PMID 29875348, 2018). "Despite of a paucity of IL-7 in the immune milieu, CTX preconditioning allowed adoptively transferred naïve tumor-specific CD4+ T cells to undergo effector differentiation and regain IL-7Rα expression, giving rise to IL-7-responsive polyfunctional CD4+ effector cells." (PMID 28939858, 2017). "Given that IL-7Rα expression is regulated by both TCR and IL-7 signaling, we went on to delineate the impact of TCR and/or IL-7 signaling on the IL-7 responsiveness of tumor-specific CD4+ T cells as well as bystander T cells." (PMID 28939858, 2017). "In contrast to Rag-/- mice, rIL-7 treatment of OT-I-reconstituted Rag-/-IL-7R-/- mice did not improve anti-tumor CD8+ T cell responses indicating that direct effects of rIL-7 on CD8+ T cells are not sufficient for successful tumor rejection." (PMID 27447484, 2016). "Activation of IL-7R increased the phosphorylation levels of downstream signaling proteins, including STAT5, AKT, and JNK, as well as the expression levels of intracellular molecules, such as CyclinD1 and MMP-9, in tumor cells." (PMID 27821177, 2016). "In conclusion, host IL-7R signaling is dispensable for rIL-7-driven CD8+ T cell expansion but not for subsequent tumor rejection." (PMID 27447484, 2016). "To this end, we analyzed TCM cells in the spleen of Il7r−/− and Ifngr1−/− tumour-bearing mice treated with or without combination therapy." (PMID 27498556, 2016).
tumor (continued). "Instead of a dysfunctional glucocorticoid-induced transcriptional response, Meijerink and colleagues identified aberrant activation of specific signaling pathways downstream of mutant IL7R, JAK1 or NRAS, or wild-type AKT as major determinants of steroid resistance in the isogenic tumor lines." (PMID 27997538, 2016). "This demonstrates that host IL-7R-deficiency does not limit LIP-associated CD8+ TM differentiation and subsequent anti-tumor immunity." (PMID 27447484, 2016). "For example, successful peptide vaccination and subsequent tumor rejection, in the absence of rIL-7 treatment, strictly required host IL-7R expression." (PMID 27447484, 2016). "Comparisons of TLS statuses within tumor samples showed that naive/central memory and effector memory phenotypes of CD8+ T cells (clusters 1 and 2), which highly expressed memory/stem-like markers including TCF7, CCR7 and IL7R, were enriched in mTLS samples and depleted in imTLS and nTLS samples." (PMID 40335494, 2025). "For example, the NeoTCR signature learned across metastatic tumour types identified high expression of the chemokines CXCL13 and CXCR6, effector genes like GZM-A/B/K, and PRF1, and inhibitory markers like TIGIT, PD1, and LAG3, as well as downregulation of stemness markers including IL7R and KLF2." (PMID 40801654, 2025). "TAMos derived from spleens of LLC tumor‐bearing mice markedly enhanced TCM cell differentiation as indicated by elevated percentages of CD44+CD62L+ T cells and increased levels of CD62L, CCR7, and IL‐7R expression during T cell antigen‐specific activation compared with vehicle or TANs." (PMID 38386350, 2024). "Interestingly, IL7R− γδ TRM upregulates inhibitory molecules CTLA4 and PDCD1 in the TME more than IL7R+ γδ TRM, indicating that IL7R+ TRM may sustain longer life and provide a longer-lasting anti-tumor effect." (PMID 39454432, 2024). "Reclustering revealed 11 distinct subclusters, of which nine were enriched in tumor and interface zones and designated as plasma B cells (clusters 2 and 10, IGHG1 +), follicular B cells (clusters 0, 3, 6, 8 and 9, MS4A1 +), immature B cells (cluster 7, IL7R +) and mast cells (cluster 5, TPSAB1 +)." (PMID 37644609, 2023). "Although IL-7 was known to promote the T-ALL proliferation and mutational activation of IL-7Rα was reported to promote the development of T-ALL, we did not observe increased tumor burden or decreased survival with rhIL-7-hyFc treatment alone in either CTCL or T-ALL PDX models." (PMID 37798328, 2023). "In concurrence with NanoString analysis of our own tumor samples, these included IFN-γ signaling genes STAT1, CXCL10, and IDO1; antigen presentation molecules HLA-DQA1 and HLA-DRB1; important T cell molecules GZMB and IL7R; and B cell–related molecules CD79A and CXCL13." (PMID 35132960, 2022). "Furthermore, CTL that does not express IL-7Rα can be modified by gene editing to restore the response to IL-7, promote the cell proliferation, and have anti-tumor activity without significantly changing their antigen dependence and specificity." (PMID 36142322, 2022). "To validate this tumor-retention mechanism, we sorted CXCR6+PD-1+ and IL7R+IL18R1+ precursor populations from the tumors of CD45.1+ congenically marked BALB/c mice and intratumorally transferred equal numbers into a 4T1 tumor growing in the mammary tissue of Rag2KO BALB/c mice." (PMID 33979626, 2021). "In addition, T3 had 120 mutations not found in the other tumours, including, for example, variants in ILF2 and IL7R, which regulate immune function, and in EP400 and POU2F1, which contribute to DNA repair mechanisms." (PMID 34299215, 2021). "In addition, the expression of BTG2, CD69, GPC3, and IL7R were considerably elevated in tumor stages III-IV as opposed to tumor stage I-II (p < 0.05)." (PMID 34881236, 2021).
tumor (continued). "To study the effects of pardaxin on tumor functions, we performed a real-time RT-PCR analysis of caspase-3, caspase-7, caspase-8, caspase-9, Bax, Bcl-2, STAT2, ATF3, STAT3, SOCS3, IL-2, cathelicidin, TNF-α, MyD88, NF-κB1, p65, IFN-β1, IFN-γ, IL-1β, IL-6, IL-7r, and IL-10." (PMID 23015777, 2012). "Although we found that IL-7R, PLD4, and ID3 are differently expressed in human PBMC of PDAC patients, the functional role of marker-expressing immune cells, spatiotemporal relationship of the markers in tumor development, and precise mechanisms for marker upregulation remain unclear." (PMID 37165046, 2023). "The combination of DDP and TCM could restore the IL-7/IL-7R signals in TCM dose-dependent manner, suggesting that DDP impaired the protective role of IL-7 during the chemotherapy but the TCM could inhibit this effect and recover the IL-7/IL7R expressions in tumor tissues." (PMID 31138762, 2019). "Tumour infiltrated T cells expressed TRAC, IL7R, CD8A, and were negative for naïve T cell marker CCR7." (PMID 38267611, 2024). "The REP protocol preferentially expanded small clones of the CD4+ phenotype (CD4, IL7R, KLRB1) in the TME, indicating that the largest exhausted T cell clones in the tumor do not expand during the expansion protocol." (PMID 37484198, 2023). "Considering that it is KIT but not IL-7R that was an independent prognostic factor, we suspected that leukemic cells with KITD816/D820 modified tumor microenvironment through affecting the profile of T cells." (PMID 35874754, 2022). "In the present study, we explored the effect of DNA methylation on the expression of the genes related to the non-coding RNAs but found no significant methylation of CD69, IL7R, and PTPRC in tumor tissues compared with that of normal tissues." (PMID 36032150, 2022). "In line with a potentially more “silenced” phenotype, these nonlesional tumor cells harbored elevated levels of CXCR4, CD69, HSPA1A, ZFP36, IL7R and TXNIP when compared to matched lesional skin." (PMID 34583709, 2021). "IL7R, NOX2-1, and NTRK1 were more frequent in CSF but not that frequent both in tumor tissues and plasma." (PMID 34671549, 2021). "However, there is no clear evidence as yet of an anti-tumor effect of such mAbs against lymphoid malignancies or solid tumors, and ligand-independent constitutive IL-7R signaling or autoactivation of downstream pathways may abrogate any antibody-dependent neutralizing effect." (PMID 28878234, 2017). "In summary, host IL-7R signaling is crucial for rIL-7-induced, CD8+ T cell-mediated tumor rejection, is not essential for CD8+ TM differentiation but promotes the expansion of granulocytes and DCs." (PMID 27447484, 2016). "We could not identify ILC1s in both the tissue and the tumor datasets, but, importantly, ILC2- and ILC3-annotated cells scored highly for IL7R expression compared with CD56bright- and CD56dim-annotated NK cells, excluding contamination by ILC1s." (PMID 38956379, 2024). "Also present were CD4+IL-7Rα+PD-1− and lower numbers of CD8+ IL-7Rα+PD-1−, likely TEM cells trafficking to the tumor site but not responding to antigen." (PMID 30042403, 2018).
infection (210 papers, 2009 to 2026). The state of being infected such as from the introduction of a foreign agent such as serum, vaccine, antigenic substance or organism. "We identified an IFNγ-dependent Type 1 immune gene signature as early as 2 days post infection (dpi) that was associated with a previously unidentified accumulation of IL-7Rα(CD127)−Eomesodermin (Eomes)+ natural killer (NK) cells at the site of infection." (PMID 31776431, 2020). "IL7R, located on 5p13, has been shown to be associated significantly with infection, inflammation, and CAD." (PMID 25343742, 2014). "The hypothesis that MAP4 can be a risk factor determining severity of infection is supported by the fact that MAP4 can interact with IL7R mRNA." (PMID 31122248, 2019). "Therefore, the dynamic changes of genes, such as TRBV4.2, TRBV7.2 (TCR components), and IL7R (associated with V(D)J recombination), may be related to different periods of infection." (PMID 36437952, 2022). "At the same time, the transcription of genes related to naïve or memory T cells, such as Sell, Il7r, Tcf7, and Lef1, decreased after infection." (PMID 41459157, 2025). "In female samples, no gene was found to be regulated at all investigated time points, whereas one down-regulated gene (Zinc finger protein 704 (ZNF704)) and two up-regulated genes (EMILIN1, IL7R) were found over the total course of infection in male samples." (PMID 40794782, 2025). "The long-term memory phenotype of pp65 and gB-specific CD4+ T cells according to IL-7R expression was more represented in control subjects with remote infection than in pregnant women with primary infection at early and late time points." (PMID 39336935, 2024). "Infection associated receptor encoding genes include CCR1 (encoding a receptor for CCL5), CRLF2 (cytokine receptor like factor 2), IL10RA, TLR2, CD2, CD48 and IL7R." (PMID 35061738, 2022). "In the lungs the progeny of transferred dKO cells are skewed towards a KLRG1+ IL7R− short lived effector (SLEC) phenotype compared to WT cells 10 days after infection." (PMID 35477960, 2022). "For example, one study reported that a c-Kithi progenitor subset positive for IL-7Rα emerged after infection of mice with Plasmodium chabaudi." (PMID 31201709, 2020). "Depletion results from both direct infection and bystander loss of memory CD4+ T cells in part attributed to dysregulated IL-7/IL-7R signaling." (PMID 31507594, 2019). "Interleukin (IL)-7R (il7r: down by 25 fold) specifically marks precursors of memory CD8+ T cells during the acute phase of infection." (PMID 30388704, 2018). "In murine models, it has been suggested that a small subset of activated T cells expressing IL-7R during primary infection give rise to long-term memory cells, while IL-7Rneg short-term effectors are destined to die after antigen clearance." (PMID 29112951, 2017). "We silenced IL-7Rα by LMP retrovirus-carried short hairpin RNA (shRNA) infection in CHILPs and then rescued expression of WT-IL-7Rα or E446A-IL-7Rα, followed by BM transplantation assays." (PMID 28794449, 2017). "Eight weeks after transplantation, IL-7Rα knockdown with empty vector infection remarkably decreased ILC3 numbers." (PMID 28794449, 2017). "In comparison, TFH cells expressed relatively low levels of IL-7R, especially at late time points post infection." (PMID 26743592, 2016). "Examining expression of c-Kit and Sca-1 on the Lin−Flt3+CD27+IL-7Rα+ population before and after infection showed that although c-Kit levels were similar, Sca-1 was found to be approximately 10-fold higher." (PMID 24825601, 2014). "IL-7Rα expression of CD8s during infection has been shown to be regulated by Gfi-1 and GABPα, however it is not yet clear if these factors also regulate functional fates." (PMID 24790593, 2013). "In the memory phase as well, 93 days after infection, the up-regulation of IL-7Rα and CD62L on OVA257–264-specific CD8+ T cells occurred similarly in both strains of mice." (PMID 22359671, 2012).